RN7SL685P (RNA, 7SL, cytoplasmic 685, pseudogene)
Gene: Miscellaneous RNA gene on chromosome 8 (100,957,883 to 100,958,180, forward strand). Ensembl gene ENSG00000242315.
Homologues: Orthologues: chimpanzee Metazoa_SRP (98% identical), macaque Metazoa_SRP (86% identical). Paralogues in human: RN7SL2 (77% identical), RN7SL1 (77% identical), RN7SL220P (76% identical), RN7SL3 (76% identical), RN7SL11P (74% identical), RN7SL147P (74% identical), RN7SL28P (74% identical), RN7SL408P (74% identical), RN7SL575P (74% identical), RN7SL44P (74% identical), RN7SL126P (73% identical), RN7SL43P (73% identical), and 703 more.